TAS1R1 (taste 1 receptor member 1)
Description:
Putative taste receptor. TAS1R1/TAS1R3 responds to the umami taste stimulus (the taste of monosodium glutamate). Sequence differences within and between species can significantly influence the selectivity and specificity of taste responses.
Synonyms: GPR70; T1R1; TR1; GM148
Tractability: Small molecule: it belongs to a druggable protein family. Antibody: its Gene Ontology location is reachable by antibodies, with high confidence; UniProt places it where antibodies can reach, with medium confidence; UniProt predicts a signal peptide or a membrane-spanning region. PROTAC: a small molecule that binds it is known.
Gene: Protein-coding gene on chromosome 1 (6,555,307 to 6,579,755, forward strand). Ensembl gene ENSG00000173662.
Subcellular location: Cell membrane
Pathways (Reactome):
Signal Transduction: Class C/3 (Metabotropic glutamate/pheromone receptors); G alpha (i) signalling events
Sensory Perception: Sensory perception of sweet, bitter, and umami (glutamate) taste
Gene Ontology:
Molecular function: taste receptor activity; G protein-coupled receptor activity
Biological process: sensory perception of umami taste; detection of chemical stimulus involved in sensory perception of taste; G protein-coupled receptor signaling pathway; sensory perception of taste
Cellular component: membrane; plasma membrane
Genetic constraint (gnomAD): Loss-of-function variants: 31 observed, 47.14 expected, observed/expected ratio (o/e) 0.66, 90% interval 0.49 to 0.89. The upper end of that interval is the gene's LOEUF score, 0.89, which puts it in group 3 of 6, group 1 being the genes least tolerant of losing a copy. Missense variants: 1,051 observed, 1,093.8 expected, observed/expected ratio (o/e) 0.96, 90% interval 0.91 to 1.01. Synonymous variants: 437 observed, 459.75 expected, observed/expected ratio (o/e) 0.95, 90% interval 0.88 to 1.03.
Homologues: Orthologues: chimpanzee TAS1R1 (99% identical), macaque TAS1R1 (93% identical), dog TAS1R1 (81% identical), pig TAS1R1 (76% identical), rat Tas1r1 (74% identical), mouse Tas1r1 (74% identical), guinea pig TAS1R1 (73% identical), rabbit TAS1R1 (72% identical). Paralogues in human: TAS1R2 (36% identical), TAS1R3 (32% identical), CASR (29% identical), GPRC6A (27% identical).
Diseases named in the same sentence as TAS1R1 in open-access papers:
TAS1R1 is named in the same sentence as 9 diseases in open-access papers, as found by Europe PMC text mining. Sharing a sentence is not in itself a finding about the gene and the disease. The quoted sentences say what the papers report.
cervical squamous cell carcinoma (1 paper, 2022). A squamous cell carcinoma arising from the cervical epithelium. "TAS1R1 had profound positive survival associations in lung adenocarcinoma–not otherwise specified (mean difference 1185 days, p = 0.0191) and cervical squamous cell carcinoma (mean difference 862 days, p = 0.0098)." (PMID 35624283, 2022).
lung adenocarcinoma (1 paper, 2022). A carcinoma that arises from the lung and is characterized by the presence of malignant glandular epithelial cells. "Increased TAS1R1 expression was associated with improved survival in lung adenocarcinoma (mean survival difference + 1185 days, p = 0.0191)." (PMID 35624283, 2022). "Similarly, increased TAS1R1 expression was associated with improved survival in lung adenocarcinoma in both analysis methods." (PMID 35624283, 2022). "Kaplan–Meier survival analyses for high- and low-expression groups of TAS1R1 was statistically significant for lung adenocarcinoma (p = 0.0069) but not for kidney papillary cell carcinoma (p = 0.051) or cervical esophageal squamous cell carcinoma (p = 0.056)." (PMID 35624283, 2022).
tumor (2 papers, 2022 to 2025). "Changes in expression for TAS1R1, TAS1R3, TAS2R4, TAS2R5, TAS2R14, TAS2R19, and TAS2R20 had survival associations in at least one tumor histology." (PMID 35624283, 2022). "Across all tumor types, the median percentage of tumors with nonsilent mutations in TAS1Rs, including TAS1R1, TAS1R2, TAS1R3, was slightly less than 1%." (PMID 35624283, 2022). "Other genes including TAS1R1 showed increased and decreased expression depending on the tumor type." (PMID 35624283, 2022).
TAS1R1 also shares sentences with these, for which no sentence is quoted: adrenocortical carcinoma (1 paper); cardiovascular disease (1); cavernous hemangioma (1); head and neck cancer (1); kidney clear cell carcinoma (1); virus infection (1).